BCL2 (BCL2 apoptosis regulator)
Diseases named in the same sentence as BCL2 in open-access papers (continued):
Sharing a sentence is not in itself a finding about the gene and the disease.
psoriasis vulgaris (2 papers, 2017 to 2023). Plaque psoriasis is the most common presentation of psoriasis. "In the GSE6710 dataset, BIRC5, NAMPT, and BCL2 had high diagnostic values in both mild and moderate-severe psoriasis vulgaris samples." (PMID 38129460, 2023). "We identified three autophagy-related genes (BIRC5, NAMPT and BCL2) with high diagnostic value for the early diagnosis of psoriasis vulgaris through bioinformatics analysis and clinical samples." (PMID 38129460, 2023). "The expression levels of BIRC5, NAMPT, and BCL2 were tested by ELISA in the blood samples of patients with psoriasis vulgaris and healthy controls." (PMID 38129460, 2023). "Previous research has found that subjects with psoriasis vulgaris had lower Bcl-2 expression than healthy subjects, perhaps due to cell proliferation of cortical cells and inflammatory stimulus in psoriasis vulgaris." (PMID 28881648, 2017). "Therefore, we considered three genes (BIRC5, NAMPT, and BCL2) as potential biomarkers for the early diagnosis of psoriasis vulgaris." (PMID 38129460, 2023). "Therefore, we hypothesized that BIRC5, NAMPT, and BCL2 might serve as biomarkers for the early diagnosis of psoriasis vulgaris." (PMID 38129460, 2023). "Therefore, we hypothesized BIRC5, NAMPT, and BCL2 as potential biomarkers for the early diagnosis of psoriasis vulgaris using bioinformatics analysis and clinical samples." (PMID 38129460, 2023). "Therefore, we proposed that BIRC5, NAMPT and BCL2 may be as potential biomarkers for the early diagnosis of psoriasis vulgaris." (PMID 38129460, 2023).
radicular cysts (2 papers, 2020). "Bcl-2 expression in OKCs was significantly higher than in radicular cysts." (PMID 33374329, 2020).
rhabdomyolysis (2 papers, 2018 to 2025). Necrosis or disintegration of skeletal muscle often followed by myoglobinuria. "In our work, the expression of apoptotic genes and the apoptotic index, the ratio of BAX/bcl2, increased in the rhabdomyolysis group." (PMID 40666175, 2025). "We found that the blockage of HDAC6 by 23BB significantly suppressed BAX/BAK and preserved Bcl-2 in the kidney tissues of rhabdomyolysis-induced AKI." (PMID 29632491, 2018).
rheumatic heart disease (2 papers, 2020 to 2022). An autoinflammatory condition following an infection with Group A Beta Hemolytic Streptococcus (GABHS), in which the heart is attacked by antibodies formed in reaction to a recent GABHS infection. "It is also demonstrated that the expression of Bcl-2 in two rheumatic heart disease patients was significantly lower than that in the control group by immunohistochemistry." (PMID 33073840, 2020). "In addition to our microarray findings, it was recently published that Bcl2 is a direct molecular target of miR-1183 in rheumatic heart disease." (PMID 35805966, 2022). "To further elucidate the relationship between expression of BCL-2 and the progression of RHD, we found that the expression of BCL-2 protein in the heart valves tissue of rheumatic heart disease patients was lower than that of mild degenerative heart disease patients (SDHVD)." (PMID 33073840, 2020). "The up-regulation of mir-1183 may affect the expression of Bcl-2 and the level of cardiomyocyte apoptosis, which may be one of the reasons for the further development of rheumatic heart disease." (PMID 33073840, 2020).
salivary gland cancer (2 papers, 2023 to 2024). A primary or metastatic malignant neoplasm that affects the major or minor salivary glands. "Finally, the results from both in vivo and in vitro experiments suggest that esculetin has pharmacological effects against salivary gland cancer by reducing the expression of Bcl‐2, a protein linked to the induction of apoptosis in tumor cells." (PMID 38062981, 2024). "As our studies have shown, a decrease in the level of the anti-apoptotic protein Bcl-2 was observed, especially after the application of fisetin to A-253 salivary gland cancer cells." (PMID 37371038, 2023).
sarcopenia (2 papers, 2021 to 2022). Progressive decline in muscle mass due to aging which results in decreased functional capacity of muscles. "Compared with the HF group, the expression levels of cleaved caspase-9, cleaved caspase-3, and BAX in the HF + sarcopenia group were significantly increased (P < 0.0001), but BCL2 did not change significantly (P > 0.05)." (PMID 35126176, 2021).
selenium deficiency (2 papers, 2019 to 2022). A nutritional deficiency disease resulting from inadequate selenium levels in the body, which can lead to impaired function of selenoproteins essential for antioxidant defense and thyroid hormone metabolism. "Selenium deficiency and T-2 toxin exposure downregulate the BCL2 gene and protein in KBD chondrocytes and cartilage tissue." (PMID 36588792, 2022).
Sertoli Cell-Only Syndrome (2 papers, 2020 to 2023). A type of male infertility in which no germ cells are visible in any of the biopsied SEMINIFEROUS TUBULES (type I) or in which germ cells are present in a minority of tubules (type II).
spinal cord injury (2 papers, 2014 to 2022). Penetrating and non-penetrating injuries to the spinal cord resulting from traumatic external forces (e.g., WOUNDS, GUNSHOT; WHIPLASH INJURIES; etc.). "Results of immunohistochemical assessment showed that the treatment with oleuropein reduced positive staining for Bax, while on the contrary, it increased positive staining for Bcl-2 in the oleuropein treatment groups after spinal cord trauma." (PMID 24842137, 2014).
spindle cell lipoma (2 papers, 2011 to 2025). A benign circumscribed tumor composed of spindled cells, adipocytes, and collagen bundles. "Spindle cell lipoma with myxoid change includes CD34-positive and bcl-2-positive spindle cells, which develop on endocapillary cells." (PMID 22185472, 2011). "In addition, the absence of bcl-2 protein and the complete retention of Rb protein in this case also represents a lack of characteristic features of spindle cell lipoma." (PMID 40376352, 2025).
splenic marginal zone lymphoma (2 papers, 2014 to 2022). Splenic marginal zone lymphoma is a rare, indolent B-cell non-Hodgkin lymphoma characterized by abnormal clonal proliferation of mature B-lymphocytes with involvement in the spleen, bone marrow and, frequently, the blood. "Bone marrow biopsy showed CD79a, CD20, and bcl‐2‐positive atypical lymphocytes, which led to the diagnosis of splenic marginal zone lymphoma." (PMID 35310319, 2022). "Bone marrow biopsy revealed proliferation of atypical lymphocytes, and immunostaining was positive for Cluster Designation (CD)79a, CD20, and bcl‐2, which led to a diagnosis of splenic marginal zone lymphoma (SMZL)." (PMID 35310319, 2022).
tauopathies (2 papers, 2015 to 2017). "Finally, various neuronal pro-survival factors (Bcl-2, Bcl-x, and surviving) have been shown to be targets of SP1, suggesting the need for in-depth analysis of the role of SP1 in tauopathies." (PMID 28367114, 2017).
thymic epithelial neoplasm (2 papers, 2007 to 2023). An epithelial neoplasm that affects the thymus gland. "Survival of thymic epithelial tumor cell lines (T1889, T1682, and TY82) depends on BCL2 and MCL1 expression, as demonstrated by siRNA knockdown." (PMID 38201593, 2023).
thymic tumors (2 papers, 2021 to 2023). "In 2020, a Meta-analysis study found that the expression of many markers was associated with higher Masaoka stage of thymic tumors, including EGFR, Glut-1, EMA, Bcl-2, etc.." (PMID 36797681, 2023).
transitional cell carcinoma (2 papers, 2003 to 2014). A malignant neoplasm arising from the transitional epithelium, usually affecting the urinary bladder, ureter, or renal pelvis. "The data available to date, describing the role played by BCL2 in transitional cell carcinoma (TCC) of the bladder, have been both limited and conflicting, with some studies showing an association with a lower tumour grade and less aggressive phenotype." (PMID 12592374, 2003).
undifferentiated carcinoma (2 papers, 1996 to 2002). A usually aggressive malignant epithelial neoplasm composed of atypical cells which do not display evidence of glandular, squamous, or transitional cell differentiation. "Expression of bcl-2 protein is common in undifferentiated carcinomas of the nasopharyngeal tract, which are nevertheless very sensitive to radiotherapy." (PMID 12454767, 2002).
uterine cancer (2 papers, 2019 to 2021). Primary or metastatic malignant neoplasm involving the uterine corpus and/or the cervix. "Furthermore, the IL-6 autocrine loop upregulated expressions of anti-apoptotic genes, such as Bcl-2, Bcl-xL, and XIAP, and drug resistance genes, such as MDR-1 and GSTpi, accompanied by the activation of the Ras/MEK/ERK and PI3K/Akt pathways in uterine cancer cells." (PMID 34226586, 2021).
vascular tumor (2 papers, 2011 to 2024). "As predictors, the immunohistochemical scores of CXLC1, CXCL2, IL6, ABCC1, LRP, BCL2, vascular tumor thrombus, ascites cancer cells, maximum tumor diameter, neoadjuvant chemotherapy, and HE4 were employed." (PMID 38509620, 2024). "IHC scores of CXCL1、CXCL2、IL6、ABCC1、LRP、BCL2, vascular tumor thrombus, ascites cancer cells, maximum tumor diameter, neoadjuvant chemotherapy, and HE4 were included in the prediction model." (PMID 38509620, 2024). "Finally, the immunohistochemical scores of CXLC1, CXCL2, IL6, ABCC1, LRP, BCL2, vascular tumor thrombus, ascites cancer cells, maximum tumor diameter, neoadjuvant chemotherapy, and HE4 were employed." (PMID 38509620, 2024).
visceral leishmaniasis (2 papers, 2016 to 2023). A severe form of leishmaniasis characterized by irregular bouts of fever, substantial weight loss, swelling of the spleen and liver, and anemia (which may be serious). "It has been shown that L. donovani causing visceral leishmaniasis can activate the expression of Bcl2, which in turn leads to the inhibition of nitric oxide (NO) production and enhances survival of the parasite." (PMID 38041167, 2023). "In a mouse model of visceral leishmaniasis (VL), Bcl-2 inhibitors partially restored the antimicrobial NO response by at least a twofold increase that resulted in significantly reduced parasite burden." (PMID 27826299, 2016).
vitamin D deficiency (2 papers, 2015 to 2025). A nutritional condition produced by a deficiency of VITAMIN D in the diet, insufficient production of vitamin D in the skin, inadequate absorption of vitamin D from the diet, or abnormal conversion of vitamin D to its bioactive metabolites. "Moreover, vitamin D deficiency has been associated with the induction of apoptosis by downregulating anti-apoptotic genes like BCL-2 and upregulating pro-apoptotic genes like BAX, underscoring its pivotal role in OSCC carcinogenesis, morbidity, and mortality." (PMID 39582404, 2025). "A reduction in calcium buffering capacity brought about by vitamin D deficiency may cause the cell to exert calcium-induced excitotoxicity, which leads to elevated levels of Bax/Bcl-2." (PMID 26020962, 2015).
, and neck cancers (1 paper, 2014). "A report indicates a correlation between heavy cigarette smoking and increased expression of Bcl2 in patients with lung, head, and neck cancers, suggesting that Bcl2 may be a primary target of carcinogens in tobacco smoke." (PMID 24967145, 2014).
abortion (1 paper, 2024). the ending of pregnancy by removing a fetus or embryo before it can survive outside the uterus. "Our findings indicated decreased Bcl-2 expression in placental tissues from spontaneous abortion cases, implying reduced cell survival signaling." (PMID 39337859, 2024).
acinar cell carcinoma (1 paper, 2019). "Polysaccharides from A. auricula-judae inhibit the proliferation of Acinar cell carcinoma and induce apoptosis in S-180 tumor cells by upregulating the expression of Bax gene and down-regulating the Bcl-2 expression." (PMID 30635591, 2019).
acute GVHD (1 paper, 2021). "It has been previously shown that inhibiting Bcl‐2 with a small molecule leads to the Treg‐dependent alleviation of acute GVHD." (PMID 34919342, 2021).
Acute hepatitis (1 paper, 2025). Acute hepatic injury resulting from inflammation typically accompanied by increased serum alanine transaminase activity. "CA nanoparticles have also demonstrated the ability to reduce inflammation and apoptosis in acute hepatitis models by decreasing levels of TNF-α, IL-1β, and IL-18, as well as inhibiting NF-κB, NLRP3, and caspase-1, while promoting Bcl-2 levels." (PMID 40869259, 2025).
adrenal carcinoma (1 paper, 2025). A carcinoma involving a adrenal gland. "Similarly, nesfatin-1 suppresses the growth of H295R, a human adrenal carcinoma cell line, by promoting apoptosis, possibly through the regulation of pro- and anti-apoptotic genes, including Bax, BCL-XL, and BCL-2, as well as ERK1/2, p38, and JNK1/2 signaling cascades." (PMID 40964608, 2025).
Adrenal insufficiency (1 paper, 2025). Insufficient production of steroid hormones (primarily cortisol) by the adrenal glands. "Therefore, the potential down-regulation of Bcl2 mentioned earlier, and the potential up-regulation of Prkar1b in the PNS cows could indicate increased apoptosis within the adrenal cortex, as well as adrenal insufficiency caused by decreased PKA activity." (PMID 40004522, 2025).
alcohol (1 paper, 2021). "The Bcl-2-involved neuroprotection of PACAP was also described in focal ischemia in mice and alcohol toxicity in rats." (PMID 33429934, 2021).
amelanotic melanoma (1 paper, 2019). A melanoma characterized by the complete absence of melanin pigment in the melanoma cells. "Within this context, other authors have demonstrated that molecules as Diazaphenothiaznes exert an antiproliferative activity in MCF7 cells and C32 human amelanotic melanoma, by regulating BAX and BCL2 gene expression." (PMID 30744145, 2019).
ampullary adenocarcinomas (1 paper, 2002).
ampullary cancers (1 paper, 2002).
anal carcinoma (1 paper, 2010). "Other apoptotic regulators that were shown to correlate with anal cancer prognosis in a single study were the Bcl-2 and M30 proteins." (PMID 21063399, 2010).
Anal fistula (1 paper, 2023). An abnormal connection between the epithelialised surface of the anal canal and the perianal skin. "In this study, we investigated the impact of Zibai ointment on wound healing by analyzing the expression levels of two key apoptosis‐related factors—B‐cell lymphoma 2 (Bcl‐2) and Bcl‐2‐associated X protein (Bax), in patients following surgery for anal fistula." (PMID 37382254, 2023). "In this study, we found that Zibai ointment effectively promoted wound healing in patients after anal fistula surgery, possibly by regulating Bcl‐2 and Bax apoptosis‐related factors." (PMID 37382254, 2023). "We found that Zibai ointment effectively promoted wound healing in patients following anal fistula surgery, possibly by regulating Bcl‐2 and Bax apoptosis‐related factors." (PMID 37382254, 2023).
apocrine tumors (1 paper, 2025). "By definition, apocrine tumors express AR and GCDFP-15 while lacking ER, PR, BCL-2, and GATA3." (PMID 41293328, 2025).
ascending aortic aneurysms (1 paper, 2016). "We also detected the apoptosis of VSMCs in patients with ascending aortic aneurysms by immunohistochemical staining of cleaved caspase-3 and Bcl-2." (PMID 26904131, 2016). "Immunohistochemistry revealed that cleaved caspase-3 staining was strong and Bcl-2 staining was weak in the ascending aortic walls of ascending aortic aneurysms relative to normal, both of which suggested increased apoptosis in the aortic walls of patients with ascending aortic aneurysms." (PMID 26904131, 2016).
astroblastoma (1 paper, 2025).
astrocytic tumor (1 paper, 2020). A glial tumor of the brain or spinal cord showing astrocytic differentiation. "This study disclosed a significant association between increasing WT1 score and the higher Bcl2 scores and labelling indices in astrocytic tumors (p<0.001)." (PMID 32856872, 2020). "Associations between WT1 expression level and the prognostic indicators of astrocytic tumors including: age IDH1 status apoptotic (Bcl2 index) and cell proliferation (Ki67 index) markers are further studied." (PMID 32856872, 2020). "WT1 score significantly associates higher Bcl2 and Ki67 labelling indices, increasing WHO tumor grade and histopathologic type of astrocytic tumors." (PMID 32856872, 2020). "IHC was applied to 75 astrocytic lesions (18 astrogliosis and 57 astrocytic tumors) using antibodies directed against WT1 clone 6F-H2, isocitrate dehydrogenase 1(IDH1), Bcl2 and Ki67." (PMID 32856872, 2020).
Atypical Meningioma (1 paper, 2017). A WHO grade II meningioma characterized by the presence of an increased mitotic activity or at least three of the following morphologic features: small cells, high cellularity, prominent nucleoli, lack of architectural pattern, and necrosis. "Higher expression of BCL2 was correlated with recurrence of benign meningiomas and a shorter time-to-recurrence for patients with atypical meningiomas." (PMID 28340489, 2017).
autism spectrum disorder (1 paper, 2019). A spectrum of developmental disorders that includes autism, and Asperger syndrome. "However, it is also important to note, that reduced BCL-2 expression is also associated with autism spectrum disorders, which further suggests the possibility that individuals with ASD are a high-risk subgroup for F induced toxicity." (PMID 30857240, 2019).
autoimmune glomerulonephritis (1 paper, 2016). An autoimmune form of glomerulonephritis (disease). "In line with our findings expression of BCL2 driven by the Vav promoter has been shown to be associated with development of heterogeneous autoimmune glomerulonephritis." (PMID 26919255, 2016).